TRBJ1-4 (T cell receptor beta joining 1-4)
Description:
J region of the variable domain of T cell receptor (TR) beta chain that participates in the antigen recognition. Alpha-beta T cell receptors are antigen specific receptors which are essential to the immune response and are present on the cell surface of T lymphocytes. Recognize peptide-major histocompatibility (MH) (pMH) complexes that are displayed by antigen presenting cells (APC), a prerequisite for efficient T cell adaptive immunity against pathogens. Binding of alpha-beta TR to pMH complex initiates TR-CD3 clustering on the cell surface and intracellular activation of LCK that phosphorylates the ITAM motifs of CD3G, CD3D, CD3E and CD247 enabling the recruitment of ZAP70. In turn ZAP70 phosphorylates LAT, which recruits numerous signaling molecules to form the LAT signalosome. The LAT signalosome propagates signal branching to three major signaling pathways, the calcium, the mitogen-activated protein kinase (MAPK) kinase and the nuclear factor NF-kappa-B (NF-kB) pathways, leading to the mobilization of transcription factors that are critical for gene expression and essential for T cell growth and differentiation. The T cell repertoire is generated in the thymus, by V-(D)-J rearrangement. This repertoire is then shaped by intrathymic selection events to generate a peripheral T cell pool of self-MH restricted, non-autoaggressive T cells. Post-thymic interaction of alpha-beta TR with the pMH complexes shapes TR structural and functional avidity.
Synonyms: TRBJ14; TCRBJ1S4
Gene: T-cell receptor joining (J) gene on chromosome 7 (142,788,225 to 142,788,275, forward strand). Ensembl gene ENSG00000281958.
Subcellular location: Cell membrane
Gene Ontology:
Cellular component: plasma membrane